INS (insulin)
Diseases named in the same sentence as INS in open-access papers (continued):
Sharing a sentence is not in itself a finding about the gene and the disease.
type 1 diabetes (continued). "Patients with type 1 diabetes continue to experience increased risk of hypoglycemic episodes and progressive weight gain resulting from intensive insulin treatment, despite the availability of a variety of insulin analogs." (PMID 19607676, 2009). "The autoimmune etiology of type 1 diabetes is also reflected by the presence of circulating autoantibodies, specific for β cell proteins including insulin (IAAs), 65-kDa isoform of GAD-1 and insulinoma-associated protein-2 (IA-2)." (PMID 20142874, 2009). "Type 1 diabetes is characterized by insulin deficiency, a loss of the insulin-producing beta cells of the pancreatic islets of Langerhans." (PMID 19607676, 2009). "Susceptibility to type 1 diabetes by 5' regulatory region of the insulin (INS) gene on chromosome 11p15.5 (IDDM2) is 10%." (PMID 20142874, 2009). "ADA 1997 has prescribed new guidelines based on pathogenic process and use of insulin requirement for the classification of type 1 diabetes." (PMID 20142874, 2009). "The T1DGC 6K SNP scan and follow-up studies confirmed that type 1 diabetes associations at INS,IFIH1 (interferon-induced helicase), and KIAA0350 and identified an additional disease association on chromosome 21q22.3 in the UBASH3A locus." (PMID 20142874, 2009). "Studies such as the DCCT have shown that intensive insulin therapy can improve glycaemic control and thereby reduce the risk of micro- and macrovascular complications faced by patients with Type 1 diabetes." (PMID 18387078, 2008). "Treatment of type 1 diabetes is to compensate for the loss ofendogenous insulin usually by infusing exogenous insulin into the body." (PMID 18437199, 2008). "Type 1 diabetes is caused by an autoimmune process resulting in a selective destruction of the pancreatic insulin-secreting β-cells." (PMID 18652676, 2008). "In that regard, the PTPN22 situation is similar to that of the insulin gene in type 1 diabetes, for which the discrepancy between numerous association reports and the absence of linkage in ASP analysis was resolved using a TDT-like analysis." (PMID 16277672, 2005). "Poor metabolic control was also associated with elevated tHcy levels in patients with type 1 diabetes, consistent with studies in which lower tHcy levels were reported for well controlled, insulin-treated type 1 diabetics than in controls." (PMID 15918903, 2005). "Type 1 diabetes mellitus (T1DM) is an autoimmune disease caused by the selective destruction of the pancreatic beta-cells causing impaired insulin secretion." (PMID 16384535, 2005). "Health-care providers should be very familiar with the perioperative management of type 1 diabetes; with individualized insulin and glucose variable infusions, young patients affected by type 1 diabetes can undergo surgery with a minimal risk." (PMID 15916471, 2005). "Type 1 diabetes is caused by the inability of a person’s pancreas to produce sufficient amounts of insulin to control their blood sugar levels and sustain life." (PMID 12805764, 2001). "In order to better simulate the normal pancreatic insulin secretion pattern, reduce blood glucose fluctuations, and lower the risk of hypoglycemia in type 1 diabetes patients, the development of an artificial pancreas system (APS) for blood glucose management has emerged." (PMID 41568163, 2026). "However, offspring of GDM mothers requiring insulin during pregnancy had a higher risk of type 1 diabetes (HR, 1.936 [1.228-3.052])." (PMID 41787464, 2026). "C-peptide, a marker of residual insulin secretion, could confirm insulin deficiency in type 1 diabetes but is rarely tested in sub-Saharan Africa." (PMID 41175199, 2026). "Insulin-dependent diabetes (type 1 diabetes, T1D) is a chronic, autoimmune process, characterized by the destruction of pancreatic β-cells by the body’s immune system, which causes the loss of the ability to produce insulin." (PMID 40427440, 2025).
type 1 diabetes (continued). "Type 1 diabetes (T1D) is a chronic autoimmune disease characterized by the destruction of pancreatic β-cells, leading to insulin deficiency and lifelong dependence on exogenous insulin." (PMID 40963622, 2025). "Type 1 diabetes (T1D) is characterized by immune-mediated destruction of pancreatic β cells, leading to insulin deficiency and hyperglycemia, necessitating lifelong exogenous insulin therapy." (PMID 41275292, 2025). "This insulin-sparing effect is clinically relevant, as it may reduce the risk of hypoglycaemia and alleviate the burden of intensive insulin therapy in type 1 diabetes management." (PMID 40629004, 2025). "If it preserves endogenous insulin production, it could be essential for improving glucose control, simplifying treatment regimens and reducing risk of complications in persons with type 1 diabetes." (PMID 41224288, 2025). "The predominance of amino acids, acyl carnitines, and fatty acid subclasses in the metabolomic profile of T1D patients is biologically plausible, as these metabolites are closely linked to insulin regulation, mitochondrial function, and lipid metabolism—key pathways disrupted in type 1 diabetes." (PMID 40852183, 2025). "Heterozygous variants in the INS gene have been reported in insulin-dependent diabetes mellitus 2 (OMIM:125852), hyperproinsulinemia (OMIM:616214), and maturity-onset diabetes of the young type 10 (MODY 10) (OMIM:613370), all exhibiting autosomal-dominant inheritance." (PMID 39859454, 2025). "Type 1 diabetes (T1D) is an autoimmune disorder that targets the insulin-producing β cells found in the pancreatic islets of Langerhans in a patient’s body, leading to loss of endogenous insulin secretion and glucose homeostasis." (PMID 41328309, 2025). "In type 1 diabetes, protein-rich meals may cause delayed glycemia, requiring tailored insulin strategies and close monitoring with continuous glucose monitoring (CGM)." (PMID 41305580, 2025). "These hormonal adaptations are essentially lost in insulin-deficient patients with type 1 diabetes." (PMID 40407447, 2025). "Furthermore, the REPOSE trial, which observed adults with type 1 diabetes, discovered that the utilization of insulin pump therapy was linked to a higher occurrence of hypoglycemia episodes compared to MDI throughout a two-year follow-up period." (PMID 41146752, 2025). "Insufficient endogenous insulin secretion is the hallmark of type 1 diabetes mellitus(T1DM)." (PMID 41165453, 2025). "Type 1 diabetes (T1D) is an autoimmune disorder where the immune system selectively destroys insulin-producing pancreatic β-cells, resulting in insulin deficiency and the need for lifelong insulin therapy." (PMID 41373764, 2025). "Atmospheric pressure changes during flights may affect insulin delivery from pumps and cause unintended metabolic consequences, including hypoglycaemia, in people with type 1 diabetes." (PMID 39496965, 2025). "Type 1 diabetes is caused by the autoimmune destruction of the insulin-secreting β-cells." (PMID 39298538, 2024). "Type 1 diabetes is caused by specific autoimmunity against the pancreatic islet beta cells, which are markedly reduced at the time of clinical diagnosis causing the need for life-long insulin replacement therapy." (PMID 38723553, 2024). "Subcutaneous insulin injections for type 1 diabetes may cause high insulin levels, which promote androgen production and may contribute to PCOS." (PMID 39616333, 2024). "In recent years, interest in understanding the immunological mechanisms underlying type 1 diabetes has increased, in turn leading to a heightened focus on addressing the primary pathology, which involves the immunological destruction of insulin-producing beta cells in the pancreas." (PMID 39749265, 2024).
type 1 diabetes (continued). "The destruction of a functional insulin-producing β-cell mass in the islets of Langerhans of the pancreas leads to an inability to correctly regulate blood glucose levels and is associated with the development of insulin-dependent diabetes." (PMID 38161208, 2024). "Moreover, the lower treatment satisfaction identified with insulin icodec in those with type 1 diabetes and the higher risk of hypoglycaemia, potentially resulting in safety issues, raise concerns and indicate the need for further investigation." (PMID 38679644, 2024). "It has been implicated that bovine insulin, milk fat, or milk protein could drive the associations between cow milk consumption and the development of type 1 diabetes." (PMID 39313195, 2024). "We examined whether the addition of an empagliflozin/metformin combination, and each drug alone, can complement insulin to improve glucometabolic parameters in overweight people with type 1 diabetes at high cardiovascular risk." (PMID 39598003, 2024). "As insulin is osteoanabolic, and insulin deficiency in type 1 diabetes affects peak bone mass, the contribution of insulin therapy may be through hypoglycaemia and falls." (PMID 38761257, 2024). "Giving insulin a bit longer if the patient has type 1 diabetes might reduce the risk of unpleasant symptoms." (PMID 39390487, 2024). "Type 1 diabetes (T1D) is caused by the autoimmune destruction of pancreatic β cells in genetically predisposed individuals, resulting in severe insulin deficiency and hyperglycemia requiring life-lasting treatment with exogenous insulin." (PMID 38182615, 2024). "Type 1 diabetes (T1D) is a chronic metabolic disorder caused by the autoimmune destruction of pancreatic β-cells, leading to the lack of endogenous insulin production and requiring lifelong insulin replacement therapy." (PMID 39334618, 2024). "However, it is essential to identify patients with type 1 diabetes, as they will require either basal insulin or an IV insulin infusion to reduce the risk of diabetic ketoacidosis due to their absolute insulin deficiency." (PMID 39199594, 2024). "Type 1 diabetes is caused by the autoimmune destruction of pancreatic insulin-producing β-cells." (PMID 39560873, 2024). "Data indicate that insulin-associated hypoglycemia is primarily observed in patients with type I diabetes undergoing insulin therapy, resulting in approximately 98,000 emergency department visits and around 30,000 hospitalizations annually in the United States." (PMID 39583394, 2024). "Individuals with type 1 diabetes typically rely on insulin replacement therapy to compensate for loss of pancreatic function, while those with type 2 often supplement lifestyle changes with oral medications that enhance insulin signaling and, in severe cases, receive exogenous insulin." (PMID 38703998, 2024). "Changes in the gut microbiome are associated with insulin dysfunction and type 1 diabetes (T1D)." (PMID 37224176, 2023). "Only a few studies on treatment with insulin analogs in type 1 diabetes have included people at high risk of severe hypoglycemia, though it may potentially be those people benefiting the most from insulin analogs." (PMID 38089060, 2023). "Greater sleepiness has been associated with fluctuating insulin and glucose concentrations in type 1 diabetes, which could explain the patterns for greater sleepiness here for the HGIP." (PMID 36841444, 2023). "Hyperglycaemia in Type 1 diabetes (T1D) results from an absolute deficiency of insulin." (PMID 37715520, 2023). "Alloxan has two distinct pathological effects, it selectively inhibits glucose induced insulin secretion through specific inhibition of glucokinase, the glucose sensor of the beta cell, and it causes a state of insulin-dependent diabetes through its ability to induce ROS formation." (PMID 37143509, 2023). "However, aerobic exercise in people with type 1 diabetes increases the risk of hypoglycaemia due to the inability to adjust for falling insulin requirements." (PMID 36879098, 2023).
type 1 diabetes (continued). "In general, type 1 diabetes may be directly or indirectly caused by damage to insulin-producing pancreatic β cells due to immune destruction." (PMID 34973115, 2023). "Finally, the Primary Oral Insulin Trial (POInT), which started recruitment in 2018, has enrolled 1050 children with a high polygenic risk score for type 1 diabetes across Belgium, Germany, Poland, Sweden and the UK." (PMID 37231274, 2023). "Type 1 diabetes (T1D) is characterized by deficient insulin production in the body." (PMID 38069300, 2023). "Type 1 diabetes mellitus (T1DM) is an autoimmune disease that leads insulin-producing β cells to death, caused by self-reactive T-cells, and represents one of the most frequent chronic diseases in children and adolescents, which incidence has increased in recent years." (PMID 37239097, 2023). "Furthermore, clinical studies have revealed that high-dose verapamil promotes insulin production in type 1 diabetes patients by delaying the loss of beta-cell function and decreasing insulin requirements." (PMID 37121975, 2023). "Type 1 diabetes is an immune-associated, destruction of insulin-producing pancreatic β cells." (PMID 36840788, 2023). "For example, in type 1 diabetes (T1D), islet autoantigens such as insulin, glutamic acid decarboxylase 65, and insulinoma-associated protein-2 have been identified in beta cell EVs, which can then be transferred to antigen-presenting cells (APCs) for processing and presentation to T cells." (PMID 37267353, 2023). "A deficiency of insulin secretion usually causes type I diabetes (T1DM)." (PMID 36978910, 2023). "Furthermore, a previous study found that raw camel milk caused an increase in insulin secretion, and reduced about 30–35% of required insulin in type 1 diabetes patients." (PMID 37570720, 2023). "However, in patients with type 1 diabetes, there is a progressive loss of glucagon response to insulin-induced hypoglycemia." (PMID 36769430, 2023). "The higher risk of type 1 diabetes in preterm born children may be explained by reduced insulin sensitivity, gut dysbiosis, exposure to antenatal corticosteroids and rapid weight gain in infancy due to catch up growth." (PMID 36869270, 2023). "However, in type 1 diabetes, the loss of beta cell function leads to inadequate insulin production and reduced inhibitory signals on alpha cells." (PMID 37409229, 2023). "Separately, whether age influences patterns of C-peptide loss or changes in insulin sensitivity in autoantibody-positive individuals who progress to stage 3 type 1 diabetes is unclear." (PMID 36459177, 2023). "DKA is a largely preventable complication in individuals with pre-existing type 1 diabetes, where infection or insulin omission are the primary causes, and in those newly presenting with type 1 diabetes, with earlier diagnosis through greater recognition of the initial symptoms." (PMID 36418578, 2023). "In contrast, type 1 diabetes results from insufficient insulin secretion, requiring insulin injections, and its cause remains unknown." (PMID 37957549, 2023). "Although SGLT2i medication and accompanying insulin reduction might cause muscle mass loss, there is, in comparison, limited evidence of skeletal muscle mass changes during SGLT2i medication in type 1 diabetes." (PMID 37424302, 2023). "Type 1 diabetes is a chronic disease that most often emerges in genetically susceptible children and adolescents following preclinical islet autoimmunity and destruction of insulin-secreting β-cells." (PMID 37170809, 2023). "Additionally, there is evidence for defective direct insulin signalling and loss of insulin-derived neurotrophic support possibly contributing to peripheral neuropathy in patients with type 1 diabetes." (PMID 36277683, 2022). "In type I diabetes, hepatic glycogen content is decreased due to deficiency of insulin." (PMID 35736457, 2022).
type 1 diabetes (continued). "Type 1 diabetes is a complex disease involving multiple factors, such as genetic susceptibility, immune dysfunction, and inflammation, and is characterized by the destruction of insulin-producing β cells." (PMID 36005597, 2022). "Type 1 diabetes mellitus (T1D) is a chronic autoimmune disease characterized by the progressive destruction of pancreatic β-cells by the immune system, leading to the absolute loss of insulin secretory function." (PMID 35359976, 2022). "Type 1 diabetes (T1D) is a chronic disease characterized by deficiency of insulin secretion." (PMID 36011925, 2022). "Type 1 diabetes mellitus (T1D) develops as a consequence of pancreatic beta-cell destruction and it is characterized by insulin deficiency, a tendency to ketosis and dependence on exogenous insulin to sustain life." (PMID 35406129, 2022). "Type 1 diabetes occurs predominantly in people < 30 years old and is generally thought to be precipitated by an immune-associated destruction of insulin-producing beta cells in the pancreas, leading to insulin deficiency and requiring exogenous insulin supplementation." (PMID 35330341, 2022). "Studies have shown that patients with insulin-dependent diabetes may die of ventricular arrhythmias caused by overeating and insulin." (PMID 36413525, 2022). "However, patients with type 1 diabetes or a history of severe hypoglycemia, or patients using insulin or sulfonylureas at a higher risk of hypoglycemia were also excluded in several studies." (PMID 35642007, 2022). "Indeed, only 2 of 13 mLCD studies (15.4%) excluded patients at a higher risk of hypoglycemia with type 1 diabetes or those using insulin or sulfonylureas, compared to 4 of 5 VLCD studies (75.0%) in our analysis." (PMID 35642007, 2022). "Some authors have mentioned the association between T2D and histocompatibility antigens, and most of the HLA haplotypes have been associated with a high risk to develop both insulin and non-insulin-dependent diabetes; most reports have also associated with MHC-II." (PMID 35627158, 2022). "Type 1 diabetes results from the autoimmune-mediated loss of insulin-producing beta-cells." (PMID 35573999, 2022). "Alhough vitamin D is necessary for normal insulin secretory responses to glucose and for maintaining healthy insulin sensitivity, it remains uncertain whether deficiency later in life increases type 1 diabetes risks." (PMID 35745248, 2022). "The detection of type 1 diabetes-associated autoantibodies targeting insulin (IAA), glutamic acid decarboxylase (GADA), tyrosine phosphatase-like protein (islet antigen-2, IA-2A) and zinc transporter-8 (ZnT8A) is currently the primary method to predict the development of type 1 diabetes." (PMID 35142878, 2022). "Type 1 diabetes (T1D) is a chronic autoimmune disease characterized by a deficiency of insulin." (PMID 35562744, 2022). "However, adult knockout mice exhibited a mild insulin-dependent diabetes associated with glucose intolerance, reduced insulin secretion, and increased insulin sensitivity." (PMID 35832432, 2022). "Therefore, this study aimed to assess the prevalence and the associated factors of hypoglycemia among type 1 diabetes (T1D) patients after insulin use at Metu Karl Referral Hospital in southwest Ethiopia." (PMID 34690922, 2021). "Nutritional factors previously identified as potentially protective against the development of type 1 diabetes, or those associated with insulin production may also be valuable for the preservation of the β-cell function." (PMID 34959363, 2021). "It has been speculated that dysfunction and/or a loss of insulin-producing cells eventually leads to human type 1 diabetes." (PMID 34769468, 2021). "For example, a type 1 diabetes susceptibility gene, Clec16a, increased rodent beta cell insulin secretion through the stimulation of a selective form of autophagy known as mitophagy, whereas humans with the susceptibility allele exhibited both reduced CLEC16A expression and increased HbA1c." (PMID 33515072, 2021).